EPCAM (epithelial cell adhesion molecule)
Diseases named in the same sentence as EPCAM in open-access papers (continued):
Sharing a sentence is not in itself a finding about the gene and the disease.
tumor (continued). "The authors showed that these CTC lines can be used to develop tumor xenograft models that express EpCAM." (PMID 32764280, 2020). "Conversely, the percentage of CK (-) EpCAM (+) cells, being raised in benign lesions, was drastically decreased with an increase in neoplasia severity (p < 0.05, U-test)." (PMID 32899940, 2020). "EpCAM is among the most studied antigens as it is known to be overexpressed on tumors of epithelial origin and is thus a bona fide tumor marker." (PMID 32731639, 2020). "Flow cytometry also revealed that 99% of the tumor cells expressed EpCAM (CD326, a marker of breast and colon CSCs)." (PMID 33143664, 2020). "TDLNs were classified as NI or I, based on the absence or presence of metastatic tumor cells (identified as EPCAM+ and CD45−)." (PMID 32601304, 2020). "In contrast, in the presence of isolated T or NK cells alone, the density of EpCAM surface expression exerts an influence on the extent of bAb-mediated tumor cell lysis." (PMID 32438548, 2020). "Taken together, the results of the present research highlight a strong similarity between ALDHhigh and CD44+/EPCAM+ cells, as suggested by cytofluorimetric analyses, tumor sphere-forming assays, and RT-PCR experiments." (PMID 32391123, 2020). "Taken together, the EpCAM+ CSC-initiated tumor growth in the NASH microenvironment represent an aggressive form of HCC tumorigenesis." (PMID 32547703, 2020). "Due to its dependency on the epithelial cell adhesion molecule (EpCAM), this system is limited to EpCAM positive tumor cells with primarily epithelial phenotypes." (PMID 32069934, 2020). "In contrast, in the absence of stemness gene amplifications, the proliferation of EpCam+ tumor cells from patient Ti41749/17 was reduced, and EpCam+ tumor cells from patient Ti41749/17 did not form mammospheres, even under the influence of IL-6." (PMID 32523653, 2020). "Histological appearance and EpCAM expression were found to be similar in primary tumor and corresponding xenograft in all cases." (PMID 32041116, 2020). "Based on that test, a patient can be affirmed to have a HER2+ tumor with at least 74% accuracy if ≥ 7% of total EpCAM+ tdEVs are CK+ and HER2+." (PMID 32787900, 2020). "Mice treated with a combination of anti-PD-1 and cabozantinib or triple treatment (chemotherapy, anti-PD-1 and cabozantinib) exhibited significantly decreased tumor weights, increased EpCAM/PD-L1-expressing cell death and increased PMN-MDSC death." (PMID 33348809, 2020). "The increased levels of EpCAM and β-catenin in EpCAM-High group suggest that EpCAM-High Hep3B cells preserved their inherent expression and properties in vivo within liver microenvironments and were responsible for tumor initiation." (PMID 32547703, 2020). "The differential association of TSPAN29 (CD9) with CD315, CD316, epithelial cell adhesion molecule (EPCAM), claudin 1 and heparin-binding EGF-like growth factor (HB-EGF) can be related to the different effects on tumor cell invasion and metastasis." (PMID 32138170, 2020). "Further, the gene expression profiling of the tumour exhibited a higher level of EPCAM, CK20, KRAS, AKT1, BRAF and CD133 expression, while lower levels of expression were observed in NANOG, MMP9 and APC genes." (PMID 33092235, 2020). "Our study shows a novel function for KLF4 in modulating the de-differentiation of tumor cells and the induction of EpCAM+/CD133+ LCSCs in HuH7 cells." (PMID 32408542, 2020). "We verified that the alveolar cells expressed relatively high levels of an alveolar marker (CLDN18), whereas both alveolar and tumor epithelial cells expressed relatively high levels of EPCAM, a well-known epithelial marker." (PMID 33083012, 2020). "EpCAM is demonstrated as cancer stem cell (CSC) or tumor initiating cell (TIC) marker, which its expression in cancer is related to the poor prognosis." (PMID 32383027, 2020).
tumor (continued). "Despite existing challenges, EpCAM remains the surface antigen of choice in clinical use to isolate circulating tumor cells (CTCs) with prognostic value and metastatic potential." (PMID 32507912, 2020). "In mice with Hep3B inoculation, the EpCAM-High group confirmed aggressive tumor incidence (n = 4/4), while the EpCAM-Low group showed only n = 1/4 mouse with successful but significant small tumor size." (PMID 32547703, 2020). "Conversely, EpCAM knockdown by siRNA sensitizes eosophageal adenocarcinoma tumor spheres to cisplatin-based chemotherapy in vitro." (PMID 32438548, 2020). "Tumor incidence and tumor burden were found to be dependent on the injected numbers of EpCAM+ Hepa1-6 cells." (PMID 32547703, 2020). "Twenty-nine patients (42%) did not exhibit any EpCAM-expression (E−/−), whereas 7 patients (10.1%) stood out with homogeneous EpCAM-expression throughout all tumor spots (E+/+)." (PMID 33225916, 2020). "Here, we present a combinatory approach with an EpCAM-directed bispecific antibody retargeting T cells via CD3 to tumor cells and EGFR-directed antibody-fusion proteins with costimulatory ligands of the B7 and TNF superfamily." (PMID 32504247, 2020). "EpCAM is highly and frequently expressed in the vast majority of carcinomas, in tumor-initiating cells, and in disseminated tumor cells, which qualified EpCAM as a potential target for cancer therapies." (PMID 32507912, 2020). "EpCAM was originally identified as a novel tumor-specific cell surface antigen and overexpressed in a large number of cancers and involved in cell migration, proliferation, and differentiation." (PMID 32814771, 2020). "Then, we systematically studied tumor-initiation abilities of EpCAM+ CSCs and EpCAM- Hepa1-6 cells in livers of animals by orthotopic inoculation." (PMID 32547703, 2020). "In the MMTV-PyMT mouse tumor model, Slug+ populations also express E-cadherin and a subpopulation of Slug+ cells also express EpCAM." (PMID 32760736, 2020). "Previous studies with anti-EpCAM DARPins fused with truncated Pseudomonas Exotoxin A (ETA’) indicated the injected protein doses necessary for suppression of tumor growth." (PMID 32392820, 2020). "Due to the relatively high surface to volume ratio, MNPs functionalized with anti-EpCAM antibody are utilized to bind to target tumor cells for in vitro separation under the external magnetic field." (PMID 32823926, 2020). "The ZR-75-1EpCAM cells form a significantly larger volume of the orthotopic tumor (P < 0.001) within the timespan of the experiment, indicating EpCAM overexpression promotes in vivo tumor growth." (PMID 33490064, 2020). "EVs were characterized using transmission electron microscopy, nanoparticle tracking analysis, and Western blotting using exosome and putative tumor markers (epithelial cell adhesion molecule (EpCAM), carbonic anhydrase 9 (CA9), CD70, CD147)." (PMID 33276608, 2020). "In conclusion, our study showed that EpCAM is a potential alternative target for FRα for tumor-specific intra-operative molecular imaging for EOC." (PMID 32545676, 2020). "The epithelial cell adhesion molecule (EpCAM) is a transmembrane glycoprotein that has received increased attention as a “universal” tumor marker for epithelial-derived cancer types." (PMID 32764280, 2020). "In primary tumor tissues, EpCAM was found to be expressed in 5/8 cellular and EV fractions, with increased concentrations of cleaved fragments in all four fractions." (PMID 33276608, 2020). "Since EpCAM overexpression leads to enrichment of CSCs and the numbers of CSCs in the cell population positively co-relates with tumor development and growth, we investigated the effect of EpCAM expression on in vivo tumor development." (PMID 33490064, 2020). "The cell-surface vimentin (CSV) was adopted to mark tumor cells with a mesenchymal phenotype, while epithelial cell adhesion molecule (EpCAM) was used to label tumor cells with an epithelial phenotype." (PMID 33143160, 2020).
tumor (continued). "The authors addressed the selection of DNA aptamers against the epithelial cell adhesion molecule (EpCAM), a marker expressed at high levels by many carcinomas as well as by circulating tumor cells." (PMID 32842557, 2020). "Regarding susceptibility to extrinsic apoptosis pathways, it is of note that the Fas receptor is detectable on half of the tumor cells in the EpCAM-“high” EC lines 2102Ep and GCT27 and negligible in the pluripotent EC line NCCIT as well as the CHC line JAR." (PMID 32438548, 2020). "As performed previously, we decided to assess the tumor sphere formation ability of CD44+/EPCAM+ cells." (PMID 32391123, 2020). "It relies on capturing epithelial cell adhesion molecule (EpCAM) positive tumor cells from whole blood, however, its broad clinical value remains elusive." (PMID 32258034, 2020). "GenoCTC allowed 90% purity, 77% separation rate, and 80% recovery of circulating tumor cells at a 90 μL/min flow rate when tested on blood spiked with epithelial cell adhesion molecule (EpCAM)-positive Michigan Cancer Foundation-7 (MCF7) cells." (PMID 32486306, 2020). "HCC in patients with expression of tumor stem cell markers such as EpCAM, PROM1 and KRT19 tend to be aggressive and chemoresistant." (PMID 33173221, 2020). "In contrast, although anti-EpCAM IgA1 induced a higher tumor-specific cell lysis than IgG1 by purified PMNs, the combination of IgA1 and IgG1 reduced tumor cell death compared to IgA alone." (PMID 33105656, 2020). "We used EpCAM (for epithelial phenotype) and Vimentin (for mesenchymal phenotype), in addition to PanCK (tumor marker), CD45 (leukocyte marker), and DAPI (nuclear marker)." (PMID 31947893, 2020). "Disseminated dormant tumor cells expressed the epithelial marker EpCAM and contained Ki67− and Ki67low fractions." (PMID 33115528, 2020). "Tumor weights were significantly lower in EpCAM-siPKCι aptamer-treated mice than Control aptamer-treated ones in both OCC1 and SK-OV3 cells." (PMID 32820156, 2020). "During EMT CTCs detach from primary tumor, loose their epithelial character by downregulation of EpCAM, infiltrate the blood circulation system and migrate into distant site of future metastasis." (PMID 32098406, 2020). "For HepG2 inoculation, both EpCAM-High and EpCAM-Low groups confirmed similar tumor incidence and growth." (PMID 32547703, 2020). "The chip with bound NeutrAvidin-NP assemblies was coated with anti-EpCAM via tetravalent biotin-NeutrAvidin binding to facilitate specific tumor cell binding." (PMID 32823926, 2020). "Epithelial cell adhesion molecule (EpCAM) is a cell surface protein that was discovered as a tumour marker of epithelial origins nearly four decades ago." (PMID 32046162, 2020). "We confirmed the presence of spatial heterogeneity of CSC-features, measured by intensity and proportion of EpCAM-expression within the same tumor nodule." (PMID 33225916, 2020). "The EpCAM-targeted MBs can bind efficiently (85%) and rapidly (within 15 min) to various epithelial tumor cells suspended in cell medium." (PMID 32098406, 2020). "The observed ectopic expression of stemness genes in patient St23784/17 led to high proliferative activity of EpCam+ tumor cells and induction of mammospheres due to the EpCam+ tumor stem cell fraction under the influence of IL-6." (PMID 32523653, 2020). "Accordingly, we have previously reported that the percentage of CTCs expressing STn was three times higher than those expressing the epithelial marker EpCAM, thus linking STn to tumor progression and dissemination." (PMID 33042825, 2020). "Ec1 showed a prominent tumor binding after 4 h, whereas after 18 h specific binding was evident for both EpCAM-targeting DARPins." (PMID 32630661, 2020). "The Epithelial Cell Adhesion Molecule (EpCAM) is cell membrane protein originally identified as an antigen derived from tumours." (PMID 32961790, 2020).
tumor (continued). "In the present study we compared antigen-monospecific therapy with dual-specific therapy based on DARPin-fusion toxic complexes targeted two different tumor-associated antigens, HER2 and EpCAM." (PMID 33081407, 2020). "The CellSearch® along with many other isolation technologies uses magnetic beads covered with anti-epithelial cell adhesion molecule (EpCAM) antibodies for positive selection of tumor cells of epithelial origin." (PMID 33042837, 2020). "Tumor cells in ascites differentially express epithelial cell adhesion molecule (EpCAM) on their surface." (PMID 32780245, 2020). "Our testing of oregano using the same model of chemically induced rat mammary carcinogenesis demonstrated decrease in CD24 and EpCAM expression in tumor cells." (PMID 32204409, 2020). "Changes in the expression profile of disseminated tumor cells can lead to failure of EpCAM-based enrichment techniques for CTC detection." (PMID 32197486, 2020). "The stem cell markers CD133 and EpCAM were significantly increased in 3D printed tumor cells, which implied that the tumor cells in the 3D printed model were superior to planar cultured cells in terms of invasion, metastasis, drug resistance, and recurrence." (PMID 32582546, 2020). "EpCAM+ circulating tumor cells (CTCs) isolated from the peripheral blood of cancer patients constitute clinically relevant and easily accessible tumor material from a single tube of blood." (PMID 32787900, 2020). "Cells identified as tumor cells were EpCAM and/or CK20 (+) (FITC) (fluorescence intensity > 400), NSE (+/−) (APC), DAPI (+) and CD45 (−) (PE)." (PMID 32005907, 2020). "EpCAM, a cell adhesion molecule, is known to be moderately expressed in normal epithelia, and to be overexpressed in certain tumor types, including RCC." (PMID 33276608, 2020). "Silencing of CA9 in the EpCAM+/CAIXhigh TICs population resulted in failed tumor initiating activity in mice xenografts." (PMID 32707920, 2020). "The epithelial cell adhesion molecule, EpCAM, belonging to the type I transmembrane protein family is glycosylated and expressed in various tissues, including human epithelial and tumor tissues as well as progenitor/stem cells." (PMID 32466488, 2020). "In the last few decades, the epithelial cell adhesion molecule (EpCAM) has received increased attention as the main membrane marker used in many enrichment technologies to isolate circulating tumor cells (CTCs)." (PMID 32764280, 2020). "In spite of EpCAM expression close to 100% of tumor cells, JAR lysis triggered by the EpCAM/CD3-bAb reaches only 25.9 ± 1.6% at 1 μg/mL and 21.2 ± 3.3% at 0.1 μg/mL bAb." (PMID 32438548, 2020). "The epithelial cadherin EpCAM has received much attention for its expression and functions in tumor cells." (PMID 32760736, 2020). "Previous immunoaffinity-based CTC enrichment methods using anti-EpCAM antibodies suffer from the limitation of missing clinically important CTCs with low EpCAM expression such as mesenchymal and stem cell-like tumor cells." (PMID 32373206, 2020). "In contrast, an EPCAM-positive cell population was observed in primary tumour-derived MRTK organoids." (PMID 32161258, 2020). "Disregarding its high abundance on epithelial tumor cells, EpCAM is also expressed on healthy human epithelia, which is a suboptimal characteristic for an imaging biomarker." (PMID 33260974, 2020). "Upon transplantation into xenografts, EpCAM+ cells promoted tumor growth in subcutaneous lesions and CD90+ cells induced high metastatic capacity in lung cells." (PMID 32466488, 2020). "Collectively, our data suggest a novel function for KLF4 in modulating the de-differentiation of tumor cells and the induction of EpCAM+/CD133+ LCSCs in HuH7 HCC cells." (PMID 32408542, 2020). "The tumor cell-enriched population was identified by anti-pan-cytokeratin (CK) and anti-EpCAM (CD326) staining." (PMID 32899940, 2020).
tumor (continued). "In conclusion, we demonstrated that the NASH liver microenvironment promotes EpCAM+ CSC-mediated HCC tumor initiation in an immunocompetent mouse model, thus recapitulating clinical conditions." (PMID 32547703, 2020). "We then analyzed the KLF4 and EpCAM expressions on tumor biopsies collected from 50 HCC patients and also identified a correlation between KLF4 and the EpCAM protein expression in HCC patients, independent of the tumor stage and differentiation status." (PMID 32408542, 2020). "In vivo, pimozide reduces the tumor burden in the nude mice xenograft model and affects cell viability on Hep3B and HepG2 cells by inhibition of·Wnt/β-catenin signaling and EpCAM gene and protein expression." (PMID 32923398, 2020). "CD90, CD13, EpCAM, and K19 have been identified in tumor cell populations, demonstrating the phenotypical heterogeneity of tumor cells." (PMID 32210805, 2020). "The in vivo data demonstrated that CD3xEpCAM significantly reduced tumor growth and prolonged survival of B16/EpCAM tumor-bearing mice." (PMID 31825302, 2019). "Qualitatively we observed that tumors treated with ICIs with or without radiation at day 23 of treatment had minimal CD8+ T cell infiltration and were largely characterized by densely packed regions of tumor cells (as denoted by EpCAM expression)." (PMID 31409394, 2019). "Bulk tumor cells were defined by the Epi+ cells expressing epithelial lineage (Epi) markers EPCAM and CD24." (PMID 31115187, 2019). "In accordance with the in vitro activity, the CD3xEpCAM bispecific antibody significantly reduced tumor growth in mice bearing B16F10/EpCAM tumors." (PMID 31825302, 2019). "It was found that the more advanced the tumor process, the less the production of characteristic proteins of epithelial origin (e.g., EpCAM) related to cell adhesion receptors." (PMID 31015522, 2019). "Data from clinical trials of EpCAM blockade suggest limited anti-tumor effects and low immune-activating efficacy." (PMID 31354723, 2019). "EMT confers on tumor cell migratory and invasive properties required for the metastatic process, thereby downregulating EpCAM expression." (PMID 31636732, 2019). "Immunofluorescence analysis of EpCAM and vimentin revealed that tumor cells constitute more than 50% of the total cell populations in all 8 gastric PDCs, making them suitable proxies for comprehensive pharmacological analysis." (PMID 31850215, 2019). "While genetically engineered BiTEs from dual scFv fragments to CD3 and either EpCAM or CD19 have shown significant anti-tumor activity in the clinic, it is advantageous to utilize readily available intact tumor specific antibodies." (PMID 31488104, 2019). "In contrast to the EGFR finding, for EpCAM retargeting a dependency on the RGD motif was observed in 2D tumor cell models." (PMID 31811202, 2019). "If its morphological characteristics are consistent with those of tumor cells, and the immune typing is shown as EpCAM+, CK+, DAPI+, and CD45-, it will be classified as tumor cells." (PMID 31729954, 2019). "We used the EpCAM-based CellSearch® Profile kit for CTC detection to facilitate the identification of only tumour cells of epithelial origin." (PMID 31718606, 2019). "In particular, the detection and molecular characterization of EpCAM-positive circulating tumor cells (CTCs) in the blood of carcinoma patients has gained considerable interest over the past ten years." (PMID 31225512, 2019). "CB-treated MCF-7 cells exhibited 80–90% expression levels of EpCAM and EGFR proteins on their surface, while CB-induced EVs also overexpressed these tumor-associated genes." (PMID 31728677, 2019). "EpCAM is thus an appealing candidate biomarker for cancer diagnosis and the evaluation of anti-tumor therapy responses." (PMID 31921310, 2019).